ORAI1 (ORAI calcium release-activated calcium modulator 1)
Diseases named in the same sentence as ORAI1 in open-access papers (continued):
Sharing a sentence is not in itself a finding about the gene and the disease.
Cachexia (1 paper, 2021). Severe weight loss, wasting of muscle, loss of appetite, and general debility related to a chronic disease. "This leads to different skeletal muscle disorders including muscular hypotonia and myopathies associated to STIM1/ORAI1 mutations, muscular dystrophies, cachexia and sarcopenia." (PMID 34685702, 2021).
chlamydia infection (1 paper, 2022). "Re-analysis of the data from Dzakah41 revealed that none of the isoforms of STIM1 or Orai1 were significantly up- or down-regulated at 20 h post chlamydia infection." (PMID 36496532, 2022).
Chorea (1 paper, 2017). Chorea (Greek for 'dance') refers to widespread arrhythmic involuntary movements of a forcible, jerky and restless fashion. "In conclusion, lack of Chorein in chorea-acanthocytosis downregulates ORAI1 expression and store operated Ca2+ entry leading to compromised neuronal cell survival." (PMID 28743945, 2017).
chorea-acanthocytosis (1 paper, 2017). Chorea-acanthocytosis (ChAc) is a form of neuroacanthocytosis and is characterized clinically by a Huntington disease-like phenotype with progressive neurological symptoms including movement disorders, psychiatric manifestations and cognitive disturbances. "In order to test whether the pathophysiology of chorea-acanthocytosis (ChAc) involves deranged neuronal regulation of the Ca2+ release activated Ca2+ channel ORAI1 and/or its regulator STIM1, experiments were performed with neurons generated from induced pluripotent stem cells (iPSCs)." (PMID 28743945, 2017).
chronic lung disease (1 paper, 2025). According to the definitions of the American and British Thoracic Societies, including pulmonary functional tests, X-rays, and CT scans for items such as fibrosis, bronchiectasis, bullae, emphysema, nodular or lymphomatous abnormalities. "We, and others, have also targeted Orai1 therapeutically, and we will also discuss how Orai1 inhibition may overcome SPLUNC1 deficiency and be beneficial for the treatment of chronic lung disease." (PMID 40589325, 2025).
ciliopathies (1 paper, 2018). "Further investigation into Orai1, Septins and their relation with ciliopathy proteins, e.g. RPGR and its interacting proteins, will shed light on the underlying mechanisms of ciliopathies." (PMID 29796181, 2018).
cystic fibrosis (1 paper, 2015). Autosomal recessive disorder caused by pathogenic variants in the CFTR gene (cystic fibrosis transmembrane conductance regulator), which encodes a chloride and bicarbonate channel expressed in epithelial cells, and follow the diagnosis criteria. "Orai1 overexpression causes the inflammatory response in cystic fibrosis and its knockdown inhibits endothelial cell migration and angiogenesis." (PMID 26166037, 2015).
diabetic cardiomyopathy (1 paper, 2024). Diabetic cardiomyopathy is a disorder of the heart muscle in people with diabetes. "Studies have shown that high glucose induces mitochondrial fission through the Orai1 calcium channel and participates in diabetic cardiomyopathy hypertrophy." (PMID 38469146, 2024).
dysplasia (1 paper, 2016). A usually neoplastic transformation of the cell, associated with altered architectural tissue patterns. "Using laser capture microdissection (LCM), we determined the level of Orai1 mRNA in dysplasia and OSCC tissues and found that Orai1 mRNA is also increased in OSCC compared to dysplastic tissues." (PMID 27259269, 2016).
Dystonia (1 paper, 2025). An abnormally increased muscular tone that causes fixed abnormal postures. "The present data now provide a direct connection between mutations in ANO3, loss of plasma membrane expression of ORAI1, disturbed Ca2+ signaling, and dystonia." (PMID 39773217, 2025).
Ebola (1 paper, 2025). "The activation of the STIM1 and Orai1 channels promotes virion assembly and budding during Ebola or Marburg virus infection." (PMID 40626726, 2025).
endometrial adenocarcinoma (1 paper, 2017). "Similarly, our unpublished data suggest that overexpression of miR-15b decreases Orai1 protein level and attenuates SOCE in human endometrial adenocarcinoma cells." (PMID 29163766, 2017).
endometrial cancer (1 paper, 2018). Primary or metastatic malignant neoplasm involving the endometrium (mucous membrane that lines the endometrial cavity). "It is noteworthy that ORAI1/STIM1 is upregulated by the serum and glucocorticoid inducible kinase (SGK1) and TGF-β in endometrial cancer cells, but downregulated by the AMP activated kinase (AMPK)." (PMID 29230527, 2018).
eosinophilia (1 paper, 2025). "Importantly, adoptive transfer of Orai1-/- or Orai1/2-/- ILC2 cells reduced airway hypersensitivity and eosinophilia compared with control ILC2 cells." (PMID 40459545, 2025).
erectile dysfunction (1 paper, 2022). Persistent or recurrent inability to achieve or to maintain an erection during sexual activity. "Furthermore, we previously reported that Orai3 was overexpressed in the human corpus cavernosum in physiologic aging, while both Orai1 and Orai3 were upregulated in the cavernosal tissue from men with erectile dysfunction." (PMID 36429103, 2022).
fibrosis (1 paper, 2022). the formation of excess fibrous connective tissue in an organ or tissue in a reparative or reactive process. "For our research, Orai3 interacted with Orai1 was significantly increased in lung from BLM‐induced fibrosis rat and fibroblast with TGF‐β1 treatment." (PMID 36128650, 2022).
follicular thyroid cancer (1 paper, 2021). "Based on these results, we then investigated the importance of the STIM1 and ORAI1 channels in follicular thyroid cancer ML-1 cells, a cell line showing the highest expression of STIM1 and ORAI1 compared to normal human thyroid cells." (PMID 34155535, 2021). "However, we found STIM1 borderline upregulated (p = 0.058) but not ORAI1 in follicular thyroid cancer tissues." (PMID 34155535, 2021).
gastrointestinal stromal tumours (1 paper, 2020). "For instance, Orai1 is predominantly upregulated in gastrointestinal stromal tumours and its inhibition (using shRNA or 2-aminoethyl diphenylborate (2-APB) and SKF-96365) decreased proliferation and induced apoptosis in GIST-T1 cells." (PMID 32575381, 2020).
Hyperinsulinemia (1 paper, 2021). An increased concentration of insulin in the blood. "Orai1 overexpression was prominent only at the early stage coinciding with hyperinsulinemia, while a higher expression of TRPC6 was obvious at the late stage." (PMID 34764278, 2021). "Our study demonstrates that Orai1 regulation in podocytes is a key Ca2+ influx mechanism regulated by growth factors and responsible for hyperinsulinemia-induced albuminuria." (PMID 34764278, 2021).
hyperreactivity (1 paper, 2023). "Together, our data suggest that Orai1 and Orai2 support pathogenic ILC2 effector function in vivo, driving the development of ILC2-dependent airway hyperreactivity." (PMID 37752127, 2023). "The results indicated that Orai1 and Orai2 are expressed on activated pulmonary ILC2s and may play a role in the development of airway hyperreactivity." (PMID 37752127, 2023).
hypersensitivity pneumonitis (1 paper, 2016). Hypersensitivity pneumonitis (HP) is a pulmonary disease with symptoms of dyspnea and cough resulting from the inhalation of an antigen to which the subject has been previously sensitized. "Neutrophil emigration was reduced by both Orai1 and Stim1 deletion in a hypersensitivity pneumonitis model that uses an immune complex-mediated reaction involving the release of chemoattractants by alveolar macrophages, which itself was normal in Orai1−/− and reduced in Stim1−/− chimeric mice." (PMID 26764049, 2016).
hypertrophic cardiomyopathy (1 paper, 2020). A condition in which the myocardium is hypertrophied without an obvious cause. "Interestingly, the integration of Orai1 in this complex promotes an enhanced ICRAC-like current involved in the development of the hypertrophic cardiomyopathy in rat ventricular myocytes." (PMID 31948094, 2020).
Infertility (1 paper, 2018). "Disruption of the widely expressed Orai1 store-operated Ca2+-channel interferes with the development of spermatozoa and entails tubular degeneration, whereas the infertility of mice lacking the TRPV6 cation channel was attributed to decreased Ca2+ reabsorption from the epididymal lumen." (PMID 29880644, 2018).
inflammatory diseases of the brain (1 paper, 2023). "Here, the authors show that the Orai1 calcium channel functions as a signaling hub in astrocytes to control astrocyte-driven brain inflammation and inflammation-induced depression-like behaviors in mice." (PMID 37679321, 2023).
inflammatory skin disease (1 paper, 2017). Inflammatory skin disorders covers a broad category that includes many conditions ranging in severity, from mild itching to grave medical health complications These disorders are common in people of all ages and races. "Recently, investigations into ion channels, such as Orai-1, TRPV1, and TRPV3, have shed new light on potential targets for the treatment of inflammatory skin diseases, such as AD." (PMID 29348776, 2017).
lupus nephritis (1 paper, 2025). Glomerulonephritis in the context of systemic lupus erythematosus. "Studies have demonstrated significantly elevated expression of Stim2 and Orai1 in lupus nephritis, and intervention with Orai1-specific small interfering RNA (siRNA) has been shown to markedly alleviate renal damage." (PMID 40989817, 2025).
metabolic syndrome (1 paper, 2017). A cluster of metabolic risk factors for CARDIOVASCULAR DISEASES and TYPE 2 DIABETES MELLITUS. "However, additional studies will be needed to determine the role of Orai1 channels in exercise-mediated regulation of metabolic syndrome." (PMID 29074621, 2017).
metastatic prostate carcinoma (1 paper, 2024). A carcinoma that arises from the prostate gland and has spread to other anatomic sites. "Statistical analysis revealed that the presence of (CK+/STIM1+/ORAI1–) phenotype significantly related (Spearman’s rho analysis, p = 0.049) with relapse in metastatic prostate cancer patients." (PMID 38903530, 2024). "Since CTCs are the major players in metastasis in the current study, we investigated for the first time the expression of STIM1, ORAI1, and KDM2B simultaneously in Circulating Tumor Cells from the same blood draw of metastatic prostate cancer patients." (PMID 38903530, 2024). "Discussion: STIM1, ORAI1, and KDM2B were overexpressed in CTCs from patients with metastatic prostate cancer." (PMID 38903530, 2024).
muscle atrophy (1 paper, 2024). The loss of muscle tissue due to inactivity or disease. "The clinical syndrome of muscle atrophy and weakness develops in humans as a result of gain-of-function mutations in the STIM1 and ORAI1 genes." (PMID 38300705, 2024).
nasopharyngeal carcinoma (1 paper, 2017). A carcinoma arising from the nasopharyngeal epithelium. "For example, down-regulation of STIM1/Orai1 counteracts the apoptosis of nasopharyngeal carcinoma cells induced by NaBu." (PMID 29089467, 2017).
oral squamous cell carcinoma (1 paper, 2023). "Recently, we reported novel evidence of Orai1 in human oral squamous cell carcinoma (OSCC) cells and human cardiac fibroblasts (HCFs)." (PMID 37759164, 2023).
osteoporosis (1 paper, 2022). A condition of reduced bone mass, with decreased cortical thickness and a decrease in the number and size of the trabeculae of cancellous bone (but normal chemical composition), resulting in increased fracture incidence. "Abnormal Orai1 expression or function may be a major cause of osteoporosis development." (PMID 35410330, 2022). "Deletion of the Orai1 gene can lead to a phenotype of osteoporosis, e.g., decreased bone density in mice, suggesting that Orai1 participates in the pathogenesis of osteoporosis." (PMID 35410330, 2022). "Some studies indicate that the deletion of the Orai1 gene can lead to a phenotype of osteoporosis, e.g., decreased bone density in mice, suggesting that Orai1 is involved in the pathogenesis of osteoporosis." (PMID 35410330, 2022). "Therefore, detailed research on the role of Orai1 in the onset of osteoporosis can yield a new idea for the biological treatment of osteoporosis." (PMID 35410330, 2022).
pulmonary fibrosis (1 paper, 2022). Chronic progressive interstitial lung disorder characterized by the replacement of the lung tissue by connective tissue, leading to progressive dyspnea, respiratory failure, or right heart failure. "Orai3 interacting with Orai1 was increased in BLM‐induced lung fibrosis and TGF‐β1‐induced fibroblast, while the Stim1 interacting with Orai1 and SOCE activity was suppressed, leading in a high and stable extracellular Ca2+ influx." (PMID 36128650, 2022).
pulmonary veno-occlusive disease (1 paper, 2025). "Orai1 expression and function are enhanced in pulmonary veno-occlusive disease–lung (PVOD-lung) tissue and SMCs from PA and veins." (PMID 41212057, 2025). "Finally, we found enhanced Orai1 expression/function in PASMCs and pulmonary vein SMCs from patients with pulmonary veno-occlusive disease." (PMID 41212057, 2025).
renal fibrosis (1 paper, 2022). A final common manifestation of a wide variety of chronic kidney diseases characterized by glomerulosclerosis and tubulointerstitial fibrosis. "Notably, a previous in vivo study has demonstrated that the inhibition of Orai1 prevents renal fibrosis." (PMID 36232526, 2022).
rhabdoid tumor (1 paper, 2021). An aggressive malignant embryonal neoplasm usually occurring during childhood. "Although STIM/ORAI1-mediated augmented SOCE has been reported to promote tumor growth and metastasis in many cancer types, STIM1 drives growth arrest in human rhabdomyosarcoma and rhabdoid tumor cell lines, ORAI1 facilitates apoptosis of PCa cells and the knockdown of ORAI1 leads to drug resistance." (PMID 34070562, 2021).
Seizure (1 paper, 2024). A seizure is an intermittent abnormality of nervous system physiology characterized by a transient occurrence of signs and/or symptoms due to abnormal excessive or synchronous neuronal activity in the brain. "Soon thereafter, ORAI1 was shown to control the excitability of mouse hippocampal GABAergic neurons, whereby loss of ORAI1 sensitised the animals to chemiconvulsant-induced epileptic seizures." (PMID 38934485, 2024).
tetanus (1 paper, 2020). A serious infectious disorder that follows wound contamination by the Gram-positive bacterium Clostridium tetani. "Specifically, recordings of the field excitatory postsynaptic potentials (fEPSPs) indicated that fEPSP slopes at 60 min following tetanus were not different from control values in Orai1 KO brain slices in both male and female mice, whereas in WT slices they were 125% of the control." (PMID 33264616, 2020).
urolithiasis (1 paper, 2021). Stone(s) within the urinary tract. "The association between the CASR, CALCR, and ORAI1 genes polymorphisms and the urolithiasis development has been shown in a number of studies conducted in Italian, Indian, and Iranian, Chinece populations by different researchers." (PMID 34054913, 2021). "When applying a comprehensive assessment of the cumulative effect of the rs12313273, rs6486795, and rs7135617 polymorphisms of the ORAI1 gene on the risk of urolithiasis development, no significant data for their cumulative effect were obtained." (PMID 34054913, 2021).
cancer (149 papers, 2012 to 2026). A tumor composed of atypical neoplastic, often pleomorphic cells that invade other tissues. "SOCE core proteins, the ER Ca2+ sensor STIM1 and the CRAC channel subunit Orai1, have been associated with cancer progression and metastasis." (PMID 39061158, 2024). "Taken together, Orai1 is associated with not only cancer cells, but also non-cancer cells, e.g., cardiac fibroblast." (PMID 37759164, 2023). "This is due to either altered expression of CRAC channel proteins, specifically, STIM1/STIM2, Orai1, and Orai3 in cancer cells compared with healthy cells or mutations in STIM1 or Orai1 proteins." (PMID 36612099, 2022). "Recently, we and another group reported that Orai1 associates with the KCa channel to participate in smooth muscle contraction as well as cancer cell migration and bone metastasis." (PMID 34744757, 2021). "This association of SK3 and Orai1 was identified to be highly relevant for the migratory abilities of cancer cells." (PMID 33466526, 2021). "Knockdown of STIM1 or Orai1 in various cancer cells is associated with inhibition of cell migration, with some exceptions." (PMID 34069353, 2021). "In fact, activating ORAI1 mutations were found in different types of cancer, including colorectal, stomach, and uterine cancers." (PMID 33171939, 2020). "Emerging evidence indicates that Orai1, a key calcium channel for store-operated Ca2+ entry, is associated with human cancer." (PMID 27259269, 2016). "A high expression of Orai1 protein is also strongly linked to poor prognosis and aggressive behavior of human cancers." (PMID 27259269, 2016). "This study provided the first evidence in support of an association between Orai1 expression and the clinical outcome of cancer patients." (PMID 25481035, 2015). "Several association studies of the SNPs of ORAI1 gene were also investigated in predicting the predisposition of diseases and cancers." (PMID 26380267, 2015). "There are few reports about the relationship between Orai1-deficiency in mice and cancer." (PMID 37759164, 2023). "Not only Orai1 but also STIM1 can be a cause of cancer development." (PMID 35681544, 2022). "Orai1, a key calcium channel, has been implicated in human cancer." (PMID 35771152, 2022). "The underlying mechanisms through which Orai1 regulates cancer progression remain to be elucidated." (PMID 36310590, 2022). "Studies increasingly show that changes in Orai1-mediated Ca2+ influx or aberrant Orai1 expression are associated with the progression of various cancers, although the exact role of Orai1 depends on the cancer type as well as the molecular or pathological subtypes." (PMID 36310590, 2022). "Growing evidence supports the hypothesis that STIM1 and Orai1 are implicated in a number of pathological processes in cancer, including human glioblastoma invasion, acute myeloid leukemia cell migration, and breast tumor cell migration." (PMID 35207698, 2022). "Indeed, altered expression of STIM1 and Orai1 is a hallmark of many cancer types, suggesting their potential value as prognostic biomarkers in cancer." (PMID 31366337, 2019). "Changes in Orai1 are also associated with increased cancer metastasis." (PMID 28165446, 2017). "Consistently, Orai1 mRNA expression was also increased in liver tumour tissues compared to adjacent normal tissue, suggesting that the changes in Orai1 expression may be associated with the biological characteristic of normal cells and cancer cells." (PMID 27878958, 2017). "As such, this present study provides the first evidence, to our knowledge, in support of an association between Orai1 expression and the clinical outcome of cancer patients and the hyperactivity of Orai1-SOCE-intracellular Ca2+ oscillations pathway in cancer cells." (PMID 24797725, 2014). "Similar approaches have been proposed for targeting other calcium signaling regulators, such as STIM1 and Orai1, in cancer therapy." (PMID 40362663, 2025).